RGS12 (regulator of G protein signaling 12)
Description:
Regulates G protein-coupled receptor signaling cascades. Inhibits signal transduction by increasing the GTPase activity of G protein alpha subunits, thereby driving them into their inactive GDP-bound form. [Isoform 5]: Behaves as a cell cycle-dependent transcriptional repressor, promoting inhibition of S-phase DNA synthesis.
Tractability: Small molecule: it belongs to a druggable protein family. Antibody: its Gene Ontology location is reachable by antibodies, with high confidence. PROTAC: UniProt records ubiquitination sites on it; ubiquitination databases record sites on it; its protein half-life has been measured; a small molecule that binds it is known.
Target class: Enzyme
Gene: Protein-coding gene on chromosome 4 (3,293,021 to 3,439,913, forward strand). Ensembl gene ENSG00000159788.
Subcellular location: Nucleus; Cytoplasm; Cell projection, dendrite; Synapse; Nucleus matrix (Isoform 5)
Subcellular location (Human Protein Atlas): Nucleoli; Nucleoplasm; Cytosol
Pathways (Reactome):
Signal Transduction: G alpha (i) signalling events
Gene Ontology:
Molecular function: GTPase regulator activity; protein binding; GTPase activator activity; GTPase activity
Biological process: G protein-coupled receptor signaling pathway; regulation of G protein-coupled receptor signaling pathway; signal transduction
Cellular component: nuclear matrix; nucleolus; nucleoplasm; nucleus; condensed nuclear chromosome; cytoplasm; dendrite; plasma membrane; synapse
Genetic constraint (gnomAD): Loss-of-function variants: 63 observed, 111.57 expected, observed/expected ratio (o/e) 0.56, 90% interval 0.46 to 0.7. The upper end of that interval is the gene's LOEUF score, 0.7, which puts it in group 2 of 6, group 1 being the genes least tolerant of losing a copy. Missense variants: 1,825 observed, 1,946.8 expected, observed/expected ratio (o/e) 0.94, 90% interval 0.9 to 0.97. Synonymous variants: 816 observed, 806.39 expected, observed/expected ratio (o/e) 1.01, 90% interval 0.95 to 1.07.
Homologues: Orthologues: chimpanzee RGS12 (99% identical), macaque RGS12 (97% identical), mouse Rgs12 (84% identical), rat Rgs12 (84% identical), dog RGS12 (82% identical), guinea pig RGS12 (81% identical), pig RGS12 (78% identical), tropical clawed frog rgs12 (65% identical). Paralogues in human: RGS14 (17% identical), RGS3 (10% identical), AXIN1 (8% identical), RGS22 (8% identical), RGS9 (8% identical), AXIN2 (8% identical), RGSL1 (7% identical), RGS11 (7% identical), RGS7 (7% identical), RGS6 (6% identical), RGS10 (6% identical), RGS20 (5% identical), and 11 more.